IL2 (interleukin 2)
Diseases named in the same sentence as IL2 in open-access papers (continued):
Sharing a sentence is not in itself a finding about the gene and the disease.
influenza (continued). "In fact, daily administration of low-dose IL-2 in patients sometimes resulted in fever, chills, influenza-like symptoms, headaches, dizziness, and arthralgia/myalgia, indicating an unmet medical need for IL-2-based therapy." (PMID 38461332, 2024). "While earlier research posited that the decreased ability of CD8+ T cells to combat influenza in the elderly wasn’t due to a decrease in the frequency of virus-specific T cells, our findings hint at IL-2 secretion playing a possible role." (PMID 37900310, 2023). "The immunization of mice with the wP vaccine in combination with influenza antigens has been shown to induce humoral responses against influenza and antigen-specific IL-2 and IFN-γ production." (PMID 37509435, 2023). "An experimental study in a severe influenza model in mice showed the high potential of DADA in reducing the cytokine storm including IL-2, IL-6, IFN-α, TNF, and IFN-γ, in addition to its role in restoring the down-regulated PDH activity caused by influenza." (PMID 35355991, 2022). "Moreover, decreasing levels of interferon gamma, interleukin 2, and tumor necrosis factor alpha, as well as the activation of the bradykinin 2 receptor signaling pathway, constitute potential mechanisms underlying the stabilization of atherosclerotic plaques by influenza vaccination." (PMID 35665329, 2022). "In a murine model of influenza infection, IL-2 was shown to inhibit Tfr development via inhibition of Bcl-6 and upregulation of Blimp-154." (PMID 35790728, 2022). "Influenza-specific CD4+ TRM cells characterize as Th1-like TRM cells secreting IFN-γ and IL-2 and contribute to enhanced protection against influenza." (PMID 36032142, 2022). "In 2006, IL-2 was co-delivered with a DNA vaccine against influenza when Henke and co-workers generated an influenza A virus bicistronic plasmid." (PMID 35891284, 2022). "We validated our technology by reproducing known experimental results, including differentiation patterns of CD4+ T cells triggered by different combinations of cytokines, metabolic regulation by IL2 in these cells, and their response to influenza infection." (PMID 34343169, 2021). "Mice were intraperitoneally infected with LCMV Armstrong and treated with the same regimen as in the influenza model (30,000 I.U. recombinant human IL-2 from day 3 to 7 post infection)." (PMID 34618873, 2021). "Other studies also demonstrated the benefit of IL-2 in controlling influenza infection, shown by the protection in mice infected with influenza A virus engineered to express IL-2, which improved CD8+ T cell immunogenicity in the mouse model." (PMID 34618873, 2021). "IL-2 expressed in response to influenza infection increases lung inflammation and enhances natural killer cells." (PMID 33808583, 2021). "Consistent with influenza infection, IL-2 treatment also promoted anti-viral immunity in acute LCMV infection, resulting in accelerated clearance of virus in serum and organs including lung, liver and kidney." (PMID 34618873, 2021). "In influenza infection in mice, IL-2 treatment competently induced the expansion of TREG cells besides the activation of CD8+ T cells." (PMID 34618873, 2021). "In the model of influenza infection, IL-2 treatment improved the viral control by enhancing effector differentiation and cytolytic function of CD8+ T cells." (PMID 34618873, 2021). "Twelve days after influenza infection, Il2cre/+; Rosa26stop-flox-Il2/+ mice have fewer Tfh cells in the draining lymph node and spleen, which is associated with a reduced frequency of germinal centre B cells." (PMID 34726156, 2021). "It has become known that antioxidants increase T cell subgroups, empower lymphocyte responses against mitogens and enhance interleukin 2 (IL-2) production, the number of natural killer cells and the response to influenza vaccines." (PMID 33681884, 2021).
influenza (continued). "Herein, we report that the combination of agonistic anti-CD40, IL-4 and IL-21 affords polyclonal B cell stimulation that was comparable to R848 and IL-2 for detection of influenza-specific memory B cells." (PMID 32069813, 2020). "IFN-γ and IL-2 together promote cellular immune responses necessary for control of influenza infection: CD8+ T cell activation and B cell differentiation." (PMID 32974217, 2020). "A seasonal influenza vaccine study revealed enhanced frequencies of CD107a NK cells induced by increased IL-2 levels and immune complexes." (PMID 32517137, 2020). "CD8+ T cells produce IL-10 in response to IFNAR signaling, IL-27, and CD4+ T cell-derived IL-2 during influenza infection in mice." (PMID 32974217, 2020). "IL-2 derived from Th1 cells promotes significant IFN-γ production by human CD56bright peripheral blood NK cells following in vitro influenza infection." (PMID 32974217, 2020). "The effect of IL-2 and granulocyte macrophage colony-stimulating factor (GM-CSF) on the efficacy of influenza vaccines was investigated previously." (PMID 32802975, 2020). "IL-2 producing CD4 T cells were used to quantify reactivity to influenza epitopes from spleen because in some strains of mice, this is the dominant cytokine expressed particularly in the spleen (and data not shown)." (PMID 31694141, 2019). "Using the 2017–18 LAIV formulation, a CD4+ IFNγ-positive or CD4+ IL2-positive T-cell response was seen in 55–68% of children to the influenza antigens tested, with approximately 80% of children showing a response to haemagglutinin or matrix and nucleoprotein." (PMID 31235405, 2019). "Only when a “strong action of IL-2” was taken into consideration by setting γ>5, 000, the level of PD-1 was suppressed for anti-influenza T cells." (PMID 30745900, 2019). "Our transcriptional analysis revealed selective upregulation of the IL-2 receptor alpha chain (Il2ra) by CD69+ CD8+ TRM cells arising in the lungs after influenza infection, potentially indicating increased responsiveness to IL-2." (PMID 30899267, 2019). "In an influenza infection model in mice, high IL-2 levels at the time of infection prevented Tfr development in a Blimp1-dependent manner." (PMID 30524440, 2018). "In the context of Influenza infection, the presence of high amount of IL-2 in the early phase leads to complete abrogation of Tfr cell formation while Tfh cells are maintained." (PMID 30150980, 2018). "The frequency of cTfh cells specific for individual influenza proteins was also substantially decreased on day 60, yet those expressing IL-2 and/or IFN-γ in response to HA and M1 were still detectable." (PMID 27231124, 2016). "We found that cTfh cells at day 7 post-TIV were able to respond to each influenza proteins, and that the specific cTfh cells expressed IL-2, IL-21, and IFN-γ at various levels." (PMID 27231124, 2016). "During influenza virus infection, impairment in GC and influenza-specific memory B cell formation was observed upon IL-2 administration." (PMID 27933060, 2016). "In HLA-A2+ donors, MHC Class I tetramer staining showed that adding both exogenous IL-2 and IL-6 resulted in greater differentiation into influenza-specific effector CD8+ T cells." (PMID 27322555, 2016). "In another study in influenza infection, Treg cell decreased the availability of IL-2 to naive CD4+ T cells and thereby promoted Tfh differentiation and enhanced GC formation and antibody response." (PMID 27933060, 2016). "After 12 days, we analysed culture supernatants for the presence of anti-influenza, anti-insulin, and anti-IL-2 IgG antibodies." (PMID 27708334, 2016). "We observed that PBMCs from older adults produce lower IL-2 levels and higher IL-6 levels following an influenza challenge when compared to those from younger individuals." (PMID 27322555, 2016).
influenza (continued). "Assays were carried out with whole (inactivated) H1N1 virus using mixed PBMC (containing detectable influenza-specific IL-2+CD4+ T cells) and pooled human AB serum containing anti-H1N1 Abs to standardize the level of influenza-specific IgG in cultures." (PMID 27233958, 2016). "Results compiled from young and older subjects also show this effect of IL-2 plus IL-6 on influenza-specific cells after 5 days of culture." (PMID 27322555, 2016). "Here we report that addition of exogenous IL-2 and IL-6 to influenza challenged PBMC, enhances the expansion and survival of the aged CD8+ T cell recall response, leading to more effector CD8+ T cells with higher cytotoxic activity." (PMID 27322555, 2016). "Significantly, more IL2 was produced when the Ncr1 zeta and Ncr1 N139 216 238A zeta BW cells were incubated with EL4 PR8 influenza compared with the BW cells expressing the O-linked Ncr1 mutants." (PMID 27462433, 2015). "IL-27 has also been shown to cooperate with IL-2 from CD4+ helper T cells to induce IL-10 through a Blimp-1 dependent mechanism during influenza infection." (PMID 25651926, 2015). "After sorting, culture and restimulation, influenza-specific IL-2+IFNγ- and IL-2+IFNγ+ cells maintained significantly biased ratios of IFNγ+ and IFNγ- cells." (PMID 24788814, 2014). "In contrast, heterogeneous expression of IFNγ in IL-2+ influenza-specific T cells appeared to be due partly to stable T cell subsets." (PMID 24788814, 2014). "Recently, we demonstrated that both IL-2 and IL-12 can serve as immunopotentiating agents in influenza vaccines tailored for the elderly." (PMID 24884849, 2014). "In this model, we propose that the majority of the anti-influenza response comprises Tbet+ Th1 cells that stochastically produce all combinations of IL-2 and IFNγ when restimulated in vitro." (PMID 24788814, 2014). "In contrast, incubation of BW NKp46 cells with 721.221 cells lead to increased IL-2 secretion, which was further enhanced following incubation with the influenza-infected 721.221 cells (721.221In)." (PMID 24009765, 2013). "The two cytokines used to analyze the influenza-specific cellular response in this study, IL-2 and IFN-γ, are produced by T cells." (PMID 23950951, 2013). "There were striking increases in influenza-specific TNFα+, IFNγ+, and IL-2+ cells in the post-infection samples." (PMID 23526940, 2013). "We cultured PBMC in vitro in the presence of RA9 peptide-pulsed autologous PMBCs, IL-7 and IL-2 from three influenza vaccinated animals (B0527, 19351 and B0547) at day 91 post initial vaccination." (PMID 22403659, 2012). "In turn, the NK cell response to influenza is enhanced by IL-2 produced by preexisting influenza-specific memory T cells, which helps to counteract killing or inhibition of NK cells by influenza virus." (PMID 22363665, 2012). "We used a polyfunctional ICS assay detecting the effector molecules IFN-γ, TNF-α, MIP-1β, IL-2 and CD107a, to compare the quality of influenza- and SIV-specific CD8 T cells." (PMID 22403659, 2012). "Pandemic influenza vaccines should preferentially activate both Th1 (IL-2, IFN-γ and TNF-α) and Th2 subsets (IL-4, IL-5, and IL-10) of T helper cells, since both are important for elimination of influenza virus from the host." (PMID 22069479, 2011). "A recent study using a novel IL-2 supplemented liposomal influenza vaccine in a group of elderly people also found superior responses with the use of IL-2." (PMID 20546588, 2010). "The GLA-SE adjuvanted Fluzone vaccine caused no adverse reactions, increased the induction of T helper type 1 (TH1)-biased cytokines such as IFNγ, TNF and IL-2, and broadened serological responses against drifted A/H1N1 and A/H3N2 influenza variants." (PMID 21060869, 2010). "Immunization of mice with B. pertussis cellular vaccines (alone or in DTP formulations) in combination with influenza vaccines was shown to induce high levels of antibodies against influenza and antigen-specific IL-2 and IFN-γ secretion." (PMID 20523738, 2010).
influenza (continued). "It has been reported that elderly people, who face higher risk from influenza infection, have decreased IL-2 production, diminished cytotoxic T-lymphocyte (CTL) activity and changes in T helper cell memory affecting the Th1 responses to influenza infection." (PMID 19274084, 2009). "Here, we show that overexpressing Prdm1 down-regulated IL-2 signaling, whereas Prdm1-deficiency enhanced IL-2 signaling in mouse CD4+ T cells and Treg cells with augmented IL-2 signaling in T cells from influenza-infected mice and during adoptive T cell transfer–induced colitis." (PMID 40680114, 2025). "aQIV-vaccinated mice also had no increase in influenza-associated inflammatory cytokines like IL-1β, TNFα, IL-2, and IL-6." (PMID 39975920, 2025). "Purified CD4+ T cells from medLNs of influenza-infected WT (Prdm1fl/fl) and Prdm1-CKO (Prdm1fl/flCD4cre) mice were treated with IL-2 for 24 hours after ex vivo influenza-specific peptide (NP311–325) stimulation and subjected to RNA sequencing (RNA-seq) analysis." (PMID 40680114, 2025). "CD4+ T cells were then stimulated with IL-2 and influenza-specific peptide (nucleoprotein NP311–325), and NP311–325 tetramer–positive CD4+ T cell populations including T follicular helper (TFH), T follicular regulatory (TFR), TEFF, and conventional Treg (cTreg) cells were analyzed." (PMID 40680114, 2025). "QIV also showed higher cytokine levels associated with influenza-induced inflammation, such as IL-1β, TNFα, IL-2, and IL-6, similar to the PBS group, which did not control viral replication well." (PMID 39975920, 2025). "Similarly, a dysfunctional antigen-specific Tfh cell compartment with an altered IL-21/IL-2 axis has been observed in individuals with impaired influenza vaccine responses." (PMID 39044830, 2024). "The anti-influenza immune activity of Cr may be mediated by the increased IL-2 that stimulated the lymphocyte transformation and improved the T lymphocyte percentage." (PMID 36837803, 2023). "While high-dose IL-2 treatment can induce vascular leak syndrome, LD IL-2 may result in transient influenza-like symptoms, or in eosinophilia driven by ILC2-produced IL-5." (PMID 37741949, 2023). "In addition to this, influenza vaccine research has been the foundation of interleukin research development for IL-1, IL-2, and IL-12." (PMID 35891284, 2022). "IL-2 is the first adjuvant in the development of influenza vaccine." (PMID 35891284, 2022). "Moreover, IFN-γ, IL-2, and IL-6 production in response to influenza protein was markedly increased in aged mice, similar to that observed in young mice." (PMID 34099809, 2021). "This demonstrated that expression of genes associated with inflammation, TNF, and IL-2 signalling in blood is negatively associated with IgG responses to seasonal influenza vaccination, irrespective of age." (PMID 34726156, 2021). "Our curation indicates that the cytokine response induced by SARS-CoV-2 is different compared to other CRS-causing respiratory viruses, as SARS-CoV-2 does not always induce specific cytokines like other coronaviruses or influenza do, such as IL-2, IL-10, IL-4, or IL-5." (PMID 33732251, 2021). "Also, the study showed that influenza vaccination reduces the levels of IFNγ, IL-2, and TNFα production and increases the levels of IL-4 in serum." (PMID 33193350, 2020). "Given that IL-2 produced from influenza-specific T cells is dependent on the NK cell driven IFN-γ response in early influenza infection, we hypothesized that NK cell ablation would impair viral clearance and increase disease severity." (PMID 32117282, 2020).
influenza (continued). "Also, it has been shown that levels of IL-2, IL-6, IL-18, TNFα, IFNγ, ET-1, sICAM-1, and sVCAM-1 are increased in influenza-infected MI patients." (PMID 33193350, 2020). "Furthermore, influenza vaccination promotes IL-2-dependent IFN-γ secretion by memory-like human NK cells in vitro following secondary exposure." (PMID 32974217, 2020). "When the frequency of CD4 T cells producing IFNγ, IL-2, or TNFα was individually quantified for each of the proteins, the pediatric population had a higher frequency of influenza-specific CD4 T cells producing TNFα compared to IFNγ across all conditions examined." (PMID 30692574, 2019). "Interestingly, Foxp3 depletion in mice was shown to compromise influenza-specific Tfh responses due to suppression of Tfh differentiation via increased IL-2 availability, thereby demonstrating a positive role for Tfr in favorable Tfh responses." (PMID 30524440, 2018). "An IL-2 independent pathway for CD4 TRM generation has also been identified in influenza infection." (PMID 30386342, 2018). "By contrast, it was demonstrated that IL-2 inhibits Tfr cell formation after Influenza infection." (PMID 30150980, 2018). "Although IL-2, IL-4, and IL-17A may be involved in the pathogenesis of bronchial asthma and influenza infection, they were undetectable in the BAL fluid from mice in this study." (PMID 28831046, 2017). "This IFNγ+ bias is particularly clear in the response to long-circulating influenza strains, whereas a new pandemic influenza strain induced a mixed influenza-specific response including both IL-2+IFNγ- and IL-2+IFNγ+ cells (abbreviated 2+γ- and 2+γ+, respectively)." (PMID 24788814, 2014). "We therefore tested IL-2 and IFNγ expression in the Th1-dominated influenza-specific response." (PMID 24788814, 2014). "As IL-2 is one of the key mitogenic cytokines involved in T cell expansion during influenza infection, reduced IL-2 production may be responsible for the reduced proliferation of activated T cells in Cd28flox/floxOx40cre/+ mice." (PMID 25347065, 2014). "Finally, acute influenza infection was associated with low plasma concentrations of inflammatory cytokines, including IFN-γ, MIP-1β, IL-2 and IL-15, and high levels of the anti-inflammatory cytokines IL-10 and IL-1ra." (PMID 21966414, 2011). "Furthermore, the percentage of activated (CD69+) influenza-specific and IL-2 producer CD8+ T-cells was higher in adult mice compared to aged ones." (PMID 19922665, 2009). "In addition, IL-2 signaling has been shown to be induced during influenza infection." (PMID 40680114, 2025). "Compared with the influenza split and subunit vaccines, the previous studies have demonstrated that whole-virion vaccines can induce stronger cell-mediated immunity toward the Th1 immune response and stimulate monocytes to secrete IL-2, IL-12 and IFN-γ by the dendritic cells." (PMID 36146744, 2022). "Notably, compared to a modest increase in CD8+/CD4+ T cell ratio induced by IL-2 treatment in the model of influenza infection, the same treatment in acute LCMV infection led to an approximately 3-fold increase in the CD8+/CD4+ T cell ratio in both spleen and inguinal lymph nodes." (PMID 34618873, 2021). "Importantly, although the young adults have higher frequencies of M1 tetramer+ cells, there is approximately a 4 to 5-fold increase in the frequency of these cells in both young and older adults in response to influenza challenge with the addition of IL-2 plus IL-6 to the cultures." (PMID 27322555, 2016). "Thus these results suggest that in older individuals, the population of influenza-specific memory T cells generated by vaccination, or re-called from earlier exposures, are defective, and that the combination of IL-2 and IL-6 is able to act together to substantially enhance responses." (PMID 27322555, 2016).